ENSG00000249240 (novel protein)
Gene: Protein-coding gene on chromosome 15 (64,841,883 to 64,930,920, forward strand). Ensembl gene ENSG00000249240.
Genetic constraint (gnomAD): Loss-of-function variants: 24 observed, 34.89 expected, observed/expected ratio (o/e) 0.69, 90% interval 0.5 to 0.97. Missense variants: 277 observed, 293.12 expected, observed/expected ratio (o/e) 0.94, 90% interval 0.86 to 1.04. Synonymous variants: 119 observed, 113.65 expected, observed/expected ratio (o/e) 1.05, 90% interval 0.9 to 1.22.